CEP290 (centrosomal protein 290)
Diseases named in the same sentence as CEP290 in open-access papers (continued):
Sharing a sentence is not in itself a finding about the gene and the disease.
Encephalocele (2 papers, 2022 to 2024). A neural tube defect characterized by sac-like protrusions of the brain and the membranes that cover it through openings in the skull. "Genes such as Centrosomal protein 290 (CEP290) have been linked with encephaloceles." (PMID 39043094, 2024).
Gruber syndrome (2 papers, 2020 to 2024). "The TZ module proteins (Meckel Gruber syndrome [MKS]/Nephronophtysis [NPHP]/Centrosomal protein of 290 kDa [CEP290]/Retinitis pigmentosa GTPase regulator-Interacting Protein 1-Like Protein [RPGRIP1L]) are known to cooperate to establish TZ formation and function." (PMID 32163404, 2020). "Studies have categorized TZ proteins into 3 functional modules: Meckel–Gruber syndrome (MKS) module, Nephronophthisis (NPHP) module, and Cep290." (PMID 38442096, 2024).
hyperopia (2 papers, 2020 to 2025). A refractive error in which rays of light entering the eye parallel to the optic axis are brought to a focus behind the retina, as a result of the eyeball being too short from front to back. "NGS analysis of LCA genes performed in patient 2–4: a 3-year-old girl with severe visual impairment including reduction of visual acuity to the level of light perception, high hyperopia, nystagmus, and strabismus revealed two variants in the CEP290 gene in a compound heterozygous state." (PMID 33308271, 2020). "Hyperopia is common in some IRDs including AD BEST1-retinopathy, RS1 and some LCA genotypes (in the current cohort: AIPL1, ALMS1, CEP290, CRB1, CRX, TULP1)." (PMID 41465105, 2025).
liver cancer (2 papers, 2022 to 2025). An epithelial or non-epithelial malignant neoplasm that arises from the liver. "This study provides strong evidence that CEP290 functions in regulating ferroptosis in liver cancer cells via the Nrf2 signaling pathway." (PMID 35271462, 2022). "CEP290 knockdown reduced proliferation, migration and invasion in Hep3B liver cancer cells while Fe2+ and malondialdehyde levels were elevated." (PMID 35271462, 2022). "To clarify the contribution of CEP290 to liver cancer progression, we examined the effect of CEP290 depletion both in vitro and in vivo." (PMID 35271462, 2022). "We confirmed expression of CEP290 in eight pairs of HCC tissues and diverse liver cancer cell lines." (PMID 35271462, 2022). "The role of CEP290 gene in cancer was described to have crucial roles in the proliferation, migration, infiltration, and ferroptosis of hepatocellular carcinoma (HCC) tissues and various liver cancer cell lines." (PMID 39995668, 2025).
macular dystrophies (2 papers, 2021 to 2024). "Notable exceptions relevant to IRD include variants in the non‐coding region upstream to PRDM13 associated with North Carolina Macular Dystrophy (OMIM 13650) and CEP290:c.2991+1655A>G, a prevalent cause of LCA in European patients." (PMID 33749171, 2021).
ptosis (2 papers, 2018 to 2021). The drooping of the upper eyelid. "Specifically, biallelic mutations were detected (i) in the PIGG gene in an 11-year-old male with ASD Asperger-type; (ii) in the PMM2 gene in a 14-year-old female with ASD, hearing loss, and ptosis; and (iii) in the CEP290 gene in a 13-year-old male with ID and attention deficit." (PMID 33921431, 2021).
syndromic (2 papers, 2018 to 2024). "The bulk of current organoid research regarding the retinal CEP290 phenotype has understandably been focused on the c.2991+1655A>G variant, but the retinal phenotype arises in many other CEP290-related syndromic diseases." (PMID 38474133, 2024).
male infertility (1 paper, 2025). The inability of the male to effect fertilization of an ovum after a specified period of unprotected intercourse. "Several satellite genes have been associated with male infertility and sperm flagellum defects in humans and mice, including PCM1, CEP131, BBS4, OFD1, CEP290, CCDC13, etc.." (PMID 40801568, 2025).
Nystagmus (1 paper, 2020). Rhythmic, involuntary oscillations of one or both eyes related to abnormality in fixation, conjugate gaze, or vestibular mechanisms. "Two CEP290 gene variants were also identified in the patient 21–58: a 1.5-year-old girl (Family 21), with a reduction of visual acuity to the level of light perception, nystagmus, and oculo-digital sign." (PMID 33308271, 2020).
Sepsis (1 paper, 2023). Sepsis is defined as life-threatening organ dysfunction caused by a dysregulated host response to infection. "Through genomic analysis, we identified seven important susceptibility genes (DNAH11, LAMA2, ABCA2, ZFAND4, CEP290, MUC20 and ENTPD1) in patients with severe burn injuries complicated with sepsis." (PMID 36659877, 2023). "At the genetic level, seven susceptibility genes for sepsis in severe burn patients were found: DNAH11, LAMA2, ABCA2, ZFAND4, CEP290, MUC20 and ENTPD1." (PMID 36659877, 2023).
kidney disease (13 papers, 2017 to 2025). "To investigate the molecular mechanisms underlying the kidney disorders observed in JSRD with CEP290 gene mutations, we depleted xCEP290 protein in Xenopus laevis embryos by injecting xCEP290 translational-blocking morpholino oligonucleotides (xCEP290-MO)." (PMID 40570958, 2025). "Previous studies have demonstrated that loss of CEP290 is linked to cilia-related kidney disorders as well as other phenotypes, including abnormalities of eyes, central nervous system, liver and heart." (PMID 40570958, 2025). "Interestingly, targeting of CDK1/2 was also shown to be effective in a Cep290/Nphp6 mouse model characterized by slowly progressive kidney disease." (PMID 34055783, 2021). "Moreover, cep290 morphants were used to search for therapies for ciliopathic renal disease, which resulted in the discovery that rapamycin and roscovitine ameliorate the symptoms." (PMID 33917666, 2021). "Disrupted CEP290 protein (also known as NPHP6) has been found to loss function binding to cellular membranes and microtubules, and proved to activate ATF4, a transcription factor associated with cAMP-dependent renal disease in JS patients." (PMID 32600475, 2020). "We demonstrate that hURECs from a JBTS patient with renal disease have elongated and disorganized primary cilia and that this ciliary phenotype is specifically associated with an absence of CEP290 protein." (PMID 28973549, 2017).
retinopathy (10 papers, 2015 to 2025). "Mouse Cep290 mutants have been used to recapitulate CEP290-retinopathy, but are limited in their ability to precisely link variant-specific CEP290 diseases with specific human clinical phenotypes." (PMID 38927641, 2024).
cancer (5 papers, 2014 to 2026). A tumor composed of atypical neoplastic, often pleomorphic cells that invade other tissues. "Moreover, we implicate several of these gene hits not only in ccRCC for the first time (BHLHB3, CAMK1, CDH13, ENPP3, KCNJ2, KSR1, PLOD2, and TCF8), but also in a cancer model for the first time (CEP290, EFCAB3, PGBD5, RAPGEF5, SSPN, and TOX2)." (PMID 24979721, 2014). "However, the biological function of CEP290 is virtually unexplored in cancers." (PMID 35271462, 2022). "In the present work, we demonstrate that centrosomal protein 290 (CEP290), which regulates cancer cell ferroptosis, growth, migration and invasion through the Nrf2 signaling pathway, is a reliable biomarker for prognosis prediction." (PMID 35271462, 2022). "In cancer cells, Sld5 depletion dispersed PCM1, AZI1, and CEP290-positive centriolar satellites without eliminating these satellite proteins, reduced dynein heavy chain expression, and destabilized dynein-dynactin localization at spindle poles." (PMID 42182163, 2026).
tumor (2 papers, 2021 to 2022). "Moreover, CEP290 knockout repressed Hep3B cell tumor formation in vivo." (PMID 35271462, 2022). "Finally, suppression of CEP290 effectively inhibited tumor growth in vivo." (PMID 35271462, 2022). "Since CEP290 silencing suppressed HCC malignant behaviors in vitro, we investigated whether CEP290 knockout inhibited tumor growth in vivo." (PMID 35271462, 2022).
autosomal recessive disease (1 paper, 2018). Autosomal recessive form of disease. "Other more representative genes were CEP290, USH2A, and CRB1 that caused autosomal recessive diseases and RPGR and CHM that caused X-linked IRD; each one accounted for about 5% of the conclusive results." (PMID 30374144, 2018).
degenerative disease (1 paper, 2017). "Over time, the phenotype of OT evolved to a progressive degenerative disease without any CEP290-associated non-ocular features." (PMID 28829391, 2017).
neurological diseases (1 paper, 2014). "Homozygous deletion of CEP290 (OMIM*610142) and ALX1 (OMIM*601527) in this region are associated with different neurological diseases, but our case is a gain of copy number." (PMID 24926319, 2014).
CEP290 also shares sentences with these, for which no sentence is quoted: retinitis pigmentosa (8 papers); Senior-Løken syndrome (4); cone dystrophy (3); developmental delay (3); genetic disorder (3); Intellectual disability (3); bacterial infection (2); COACH syndrome (2); cyst (2); early onset retinal dystrophy (2); hepatic disease (2); Hepatic fibrosis (2); Joubert syndrome and related disorders (2); keratoconus (2); Ventriculomegaly (2); 22q11.2 deletion syndrome (1); age-related macular degeneration (1); albinism (1); asthenozoospermia (1); Atrophy (1); autosomal dominant retinitis pigmentosa (1); Bardet-Biedl syndrome 14 (1); Bietti crystalline dystrophy (1); biotinidase deficiency (1); Branchio-otic syndrome (1); cardiac disease (1); cerebellar ataxia (1); choroideremia (1); Cognitive impairment (1); colorectal cancer (1).
A further 38 diseases each share a sentence with CEP290 in 1 paper.